TNF (tumor necrosis factor)
Diseases named in the same sentence as TNF in open-access papers (continued):
Sharing a sentence is not in itself a finding about the gene and the disease.
psoriasis (continued). "The increase in TNF expression at baseline in CD56bright cells has already been evidenced in some inflammatory skin diseases (lichen planus, psoriasis, Sezary’s syndrome, and mycosis fungoides), as well as in our findings in adults with AD26,27." (PMID 38302650, 2024). "These treatments function by specifically focusing on important cytokines or proteins on the surface of cells that are involved in the development of psoriasis, such as tumor necrosis factor-alpha (TNF-α), interleukin-17 (IL-17), and interleukin-23 (IL-23)." (PMID 39359925, 2024). "On the other hand, arterial stiffness and signs of vascular remodeling were found more frequently in RA than in PsA, with the potential role of efficient anti-TNF treatment in patients with PsA and psoriasis explaining this finding." (PMID 38522049, 2024). "In conclusion, TNF-α inhibitors are highly effective in reducing atherosclerosis progression in psoriasis patients, consistently improving vascular health markers like CIMT, aPWV, FAI, and CRP." (PMID 39739136, 2024). "Etanercept or infliximab are known to be effective in the treatment of psoriasis, in which T cells and dendritic cells activated by tumor necrosis factor (TNF) accumulate and produce cytokines such as TNF-α and IL-23." (PMID 38739932, 2024). "Both diseases involve cytokines such as TNF-α and IL-23, making anti-TNF and IL-23 inhibitors effective in managing moderate to severe cases of psoriasis and IBD​." (PMID 39463646, 2024). "Based on current evidence, it appears that the use of anti-TNF-α for psoriasis and anti-IL-4/13 for atopic dermatitis are inversely related." (PMID 38521706, 2024). "Curiously, in patients with psoriasis, ustekinumab treatment have also led to insignificant weight gains, compared with anti-TNFα therapy." (PMID 38822800, 2024). "In psoriasis, moreover, the cytokines IL-17, IL-22, TNF-α and IFN-γ promote the secretion of antimicrobial peptides (AMPs) such as human β-defensins and the cathelicidin LL-37 (encoded by CAMP) by keratinocytes." (PMID 38251799, 2024). "In IMQ-induced psoriasis skin, both S1pr2-/- and S1pr2fl/fl K14-Cre mice showed higher expressions of proinflammatory cytokines such as TNF-α, IL-17A, and IL-1β together with higher expressions of MyD88/NF-κB pathway compared to the wild-type mice." (PMID 39391307, 2024). "In the case of psoriasis, it has been identified that specific cytokines (TNF-α, IL-17, and IL-22) secreted by subsets of T-cells are responsible." (PMID 39712184, 2024). "Among these, only 1050 ICSRs (0.3%) described cases of pregnant women with psoriasis treated with an anti-TNF drug." (PMID 39065754, 2024). "APS improved psoriasis-like dermatitis in mice by inhibiting skin macrophage infiltration and reducing serum levels of TNF-α, IL-1β and IL-6." (PMID 39338338, 2024). "Downregulation of this gene results in activation of the p38 MAPK pathway, which in turn increases secretion of IL-17 and TNF-α byTh1 and Th17 and drives the inflammatory process in psoriasis." (PMID 39766858, 2024). "Overexpression of TNF-α results in excessive production of proinflammatory cytokines like IL-6, IL-8, IL-12, and IL-18, driving a transformation of the psoriasis phenotype to pustular psoriasis." (PMID 38695018, 2024). "In a study evaluating the treatment of psoriasis with IL-17A and TNF-α inhibitors, it was observed that the differential expression of the protein TYMP before and after treatment was significant." (PMID 39480805, 2024). "In patients with psoriasis, there is an imbalance between the levels of pro- and anti-inflammatory adipokines (TNF-α, IL-6, leptin, resistin, and vifastin which increases, and adiponectin which decreases)." (PMID 38473907, 2024). "Over the years when biologic psoriasis therapies (TNF inhibitors, IL-12/23 inhibitors, IL-23 inhibitors, and IL-17 inhibitors) have been used in psoriasis patients, reports of major cardiovascular events (MACEs) have emerged." (PMID 38384460, 2024).
psoriasis (continued). "Paradoxically, TNF-α antagonists can also induce autoimmune diseases being systemic vasculitis, systemic lupus erythematosus, and psoriasis, the most common." (PMID 39529874, 2024). "Recent studies have suggested that CBD’s effects on skin diseases such as allergic contact dermatitis, acne, and psoriasis are attributed to the inhibition of pro-inflammatory cytokines such as TNF-α, IL-1β, IL-6, and IL-17A." (PMID 39335596, 2024). "TNF-α inhibitors, which are effective in treating psoriasis, paradoxically induce psoriasis themselves, termed TNFiIP, also named paradoxical psoriasis." (PMID 39927272, 2024). "AD models can be generated by adding TH2 cytokines such as IL-4 and IL-13, and TNF-α, whereas psoriasis models are induced by treating skin models with cytokine cocktails based on IL-17, IL-22 and TNF-α." (PMID 38251799, 2024). "In the psoriasis-like immune microenvironment, simulated by pro-inflammatory factors such as TNFα, primary human epidermal keratinocytes exhibit typical pyroptotic morphology characterized by cell swelling and bubbling." (PMID 39595526, 2024). "Considering the anti-inflammatory effect of A3 receptor engagement in RA patients by modulating TNF-α and NF-κB, A3 agonists for the therapy of RA, as well as for psoriasis, are currently tested in clinical trials or have been evaluated already." (PMID 38891997, 2024). "In vivo experiments confirmed that a 1.38-fold knockdown of TNFα was observed with PLN-TPPS2a-TNFα siRNA compared to the psoriasis group, suggesting that it enhanced the preventive effect of psoriatic plaques." (PMID 39598508, 2024). "In the chronic phase of classical psoriasis, TNF-α and IL-23 activate potentially autoreactive CD8+ T cells while forming a negative feedback loop with interferon-α production." (PMID 39781163, 2024). "TNF-α serves as a crucial inflammatory cytokine highly evolved in psoriatic lesions, playing a central role in the development of psoriasis." (PMID 39311381, 2024). "Psoriasis-like erythematous appearance and microscopic features were significantly reduced, along with a notable decrease in the tissue gene expression of core psoriasis cytokines, such as IL-23, IL-17A, IL-22, TNF-α, and IL-6, after the capsaicin treatment." (PMID 39338338, 2024). "The development and progression of psoriasis are influenced by pro-inflammatory cytokines such as IL-12, IL-23, and TNF." (PMID 39777115, 2024). "A subsequent study with a larger sample size and diverse sample characteristics is essential to confirm the relationship between hs-CRP, TNF-α, and atherosclerosis in psoriasis patients." (PMID 39104857, 2024). "In a small case series, 6 of 12 women with psoriasis received an anti-TNF drug in the first trimester." (PMID 39065754, 2024). "TNF-α inhibitors interrupt the inflammatory cycle by neutralizing TNF-α, providing both rapid and sustained relief of symptoms associated with severe psoriasis." (PMID 39767248, 2024). "The recent development of IL-17 and IL-23 inhibitors represent important additions to the psoriasis armamentarium, providing new options when TNF inhibitors are inadequate or intolerable." (PMID 38348339, 2024). "Our study aimed to evaluate the safety profile of anti-TNF drugs in pregnant women with psoriasis, with a focus on certolizumab, which is considered safer than adalimumab, etanercept, infliximab, and golimumab." (PMID 39065754, 2024). "Anti-TNF-alpha agents, such as adalimumab and etanercept, inhibit tumor necrosis factor-alpha, a pro-inflammatory cytokine involved in the pathogenesis of psoriasis." (PMID 39518685, 2024). "In an Italian series of ten patients with HIV infection and psoriasis, published in 2017, six received anti-TNF (four etanercept and two adalimumab), and four received ustekinumab." (PMID 38238209, 2024). "On one hand, it notably inhibits plasmacytoid DCs from secreting interferon (IFN)-α, often resulting in exacerbated or paradoxical psoriasis during TNF-α inhibitor treatment." (PMID 39311381, 2024).
psoriasis (continued). "Conversely, resistin, a pro-inflammatory adipocytokine associated with Th1/Th17 immune responses, was significantly elevated by TNF-α alone or in combination with IL-17, supporting its role in exacerbating inflammatory pathways relevant to psoriasis." (PMID 39769200, 2024). "Except for Infliximab, an anti-TNFα biologic administrated by an intravenous infusion, all the biologics targeting psoriasis are delivered by subcutaneous injections as proceeded similarly in this work using the tick protease inhibitors." (PMID 38444844, 2024). "Cytokines that upregulated in psoriasis patients include TNF-α, IL-1β, IL-12, and IL-17A were also involved in the development of lung cancer, indicating that both psoriasis and lung cancer are closely involved with immune alteration." (PMID 36604675, 2023). "For instance, In a study on psoriasis patients, the use of TNF-α inhibitors increased overall infection and upper respiratory tract infection by up to 7% compared with placebo, higher than the rates with IL-17 and IL-12/23 inhibitors." (PMID 38029150, 2023). "It had been demonstrated that curcumin can reduce various inflammatory factors such as TNF‐α, IFN‐γ, IL‐22, and IL‐23 in mouse serum, which are closely involved in the pathogenic mechanism of psoriasis." (PMID 37647442, 2023). "There is growing concern related to multiple clinical cases reporting an unexpected onset of psoriasis following the use of TNF inhibitors." (PMID 37369753, 2023). "Vascular endothelial growth factor, hypoxia-inducible factor, tumor necrosis factor, IL-8 and angiopoietin are generally considered to be the main players in psoriasis angiogenesis." (PMID 37072847, 2023). "Previous studies have demonstrated that this signaling molecule is involved in the pathogenesis of psoriasis by upregulating the production of chemokines and pro-inflammatory cytokines, such as IL-6, TNF-α and IL-17A." (PMID 36839031, 2023). "The efficacy of treatment of psoriasis with TNF-α inhibitors, IL-17 inhibitors, and IL-23 inhibitors as biological agents that suppress the function of specific cytokines has been demonstrated." (PMID 37834081, 2023). "It was proven to act by inhibition of IL-8 (levels of mRNA) and protein release and TNF, both of which are the main mediators of the inflammatory process of psoriasis." (PMID 36986611, 2023). "In the past decade, the management of psoriasis patients has been revolutionized by the introduction of biological therapies, such as anti-TNF-α antibody and anti-IL-12/23 antibody (anti-IL-12 antibody) treatment." (PMID 37833247, 2023). "TNF-α, involved in the regulation of immune and inflammatory responses, is related to the development of psoriasis." (PMID 37298949, 2023). "Tumor necrosis factor (TNF), a drug target in the treatment of inflammatory diseases such as psoriasis, was ranked 1,558th (top 8%; Exome-psoriasis) prior to and 182nd (top 0.98%; r = 0.6) post-propagation in the STRING network." (PMID 37492104, 2023). "In our study, we treated psoriasis-induced mice and IL-22- or TNF-α-stimulated HaCaT cells with SFN and subsequently measured the activation status of the STAT3 and NF-κB pathways." (PMID 38007430, 2023). "TNF-α inhibitors currently in use to treat psoriasis are Etanercept, Infliximab, Adalimumab, and Certolizumab." (PMID 38003284, 2023). "In psoriasis, Tc1 cells release IFN-γ, IL-2, and TNF-α, playing different roles during the development of psoriasis." (PMID 37942312, 2023). "Recently, there has been growing concern over TNF inhibitor-induced psoriasis, with many case reports detailing the onset of psoriasis in patients using TNF inhibitors, such as certolizumab pegol." (PMID 37369753, 2023). "In phase II trials, guselkumab, an IgG1 anti-IL-23p19 mAb, outperformed the anti-TNF mAb adalimumab and was approved for the treatment of psoriasis." (PMID 36831151, 2023).
psoriasis (continued). "We report a patient with reactivation of latent histoplasmosis six months after starting an anti-TNF-⍺ inhibitor for the treatment of psoriasis." (PMID 37720115, 2023). "In the general population, psoriasis is mainly driven by the activation of the Th17 pathway, and several cytokines, including tumor necrosis factor alpha (TNF-α), IL-23, IL-17, and IL22, play important roles in its pathogenesis." (PMID 37504358, 2023). "The four classes of biologics used to treat psoriasis are TNF inhibitors, IL-12/23 inhibitors, IL-17 inhibitors and IL-23 inhibitors." (PMID 37111283, 2023). "The aggravation of symptoms was related to increased production of the psoriasis-related proinflammatory cytokines IL-6 and TNF-α." (PMID 36982669, 2023). "As an innovative biologic therapy, mAb anti-TNF-alpha and anti-IL have shown considerable efficacy in treating psoriasis, including nail psoriasis." (PMID 37627974, 2023). "A recent systematic review of active comparator-controlled clinical trials for psoriasis concluded that the newer biologic agents, namely, IL-17 and Il-12/23 inhibitors, are more effective than TNF-a inhibitors in reducing disease severity." (PMID 37240864, 2023). "Clinical data with therapeutic monoclonal antibodies have validated the role of anti-TNF, antiIL-17 and anti-IL-23 therapy in moderate to severe psoriasis." (PMID 37215725, 2023). "Angiogenic mediators such as vascular endothelial growth (VEGF), tumor necrosis factor (TNF), interleukin (IL)-8, and IL-17 are over-expressed in psoriasis and expedite the abnormality." (PMID 36769305, 2023). "Since TNF is involved in some autoimmune and inflammatory diseases, our result implicates the therapeutic potential of miR-22 for psoriasis treatment by targeting the production of TNF." (PMID 37469388, 2023). "Paradoxically, TNF-α blockade can lead to psoriasis and erythema nodosum because of a dysregulated type I interferon response." (PMID 37697374, 2023). "TNF-α inhibitor: It is acknowledged as a crucial regulatory cytokine in psoriasis and other chronic immune-related inflammatory disorders." (PMID 37965393, 2023). "Initially successful in treating rheumatoid disorders, TNF-α inhibitors were later extended to include the treatment of psoriasis and psoriatic arthritis (PsA)." (PMID 38239345, 2023). "The results of studies suggest that resistin plays an important role in the development of psoriasis by affecting inflammatory factors such as TNF-α and reducing the population of Foxp3+ Treg cells." (PMID 36675592, 2023). "They found that Th1 cells secreted IFNγ and TNF-α and that Th2 cells secreted IL-4, IL-5, and IL-13, thereby defining psoriasis as a Th1 disease." (PMID 38003284, 2023). "In turn, pro-inflammatory cytokines such as TNF-α, IL-1β, and IL-6, which are increased in psoriasis, can activate LOX-1, promoting the uptake of ox-LDL by macrophages." (PMID 37234169, 2023). "Cytokines (tumor necrosis factor-α (TNF-α), interleukin (IL)-17), which are important in the pathogenesis of psoriasis, have been shown to affect cholesterol and lipid metabolism." (PMID 37234169, 2023). "For TNF-α inhibitors, for example, cases of treatment-induced or exacerbations of skin manifestations, such as psoriasis were reported." (PMID 37568441, 2023). "Our study provided patient-specific QSP models of the MoA of CZP, a PEGylated Fab humanized monoclonal antibody against TNF-alpha, in a vPop of patients with moderate-to-severe psoriasis, based on PBPK and SB models." (PMID 37809085, 2023). "The efficacy of selective biologics targeting tumor necrosis factor (TNF), IL-23, and IL-17 has demonstrated their pivotal roles in the pathogenesis of psoriasis." (PMID 37841246, 2023). "The results indicate that adiponectin exerts anti-inflammatory effects in psoriasis by reducing the production of IL-6 and TNF-α." (PMID 36675592, 2023).
psoriasis (continued). "Currently, the most successful therapies against psoriasis are biologic agents targeting IL17A or TNFα, but there are several safety concerns about the usage of such therapies, and there is a constant search for better-tolerated solutions." (PMID 37351597, 2023). "Treatments for psoriasis have also been developed to inhibitor NF-κB activation or downstream transcription factors, including TNF-α or IL-17/IL-23." (PMID 38203337, 2023). "Conversely, the overexpressed IL-17 cytokine in psoriasis leads to the activation of the NF-ᴋB pathway and the production of other proinflammatory cytokines-IL-1β, IL-6, and TNF-α." (PMID 38003284, 2023). "TNF-α inhibitors including infliximab, adalimumab, etanercept, and certolizumab pegol are clinically effective in psoriasis." (PMID 37881433, 2023). "Anti-tumor necrosis factor-alpha (TNF-⍺) inhibitors are commonly used in the treatment of inflammatory conditions such as psoriasis." (PMID 37720115, 2023). "Due to the central role TNF-α plays in the pathogenesis of psoriasis, TNF-α inhibitors were the first biologic drug approved for the treatment of psoriasis." (PMID 37664349, 2023). "The TNF-α is an inflammatory molecule crucial for psoriasis pathophysiology, as shown by the significant antipsoriatic effect of biological molecules (infliximab, etanercept, and adalimumab), which block its action." (PMID 36903291, 2023). "The first generation of biological drugs in psoriasis consists of the anti-TNF agents (TNF inhibitors; TNFi), incorporating four mAbs (Infliximab, Adalimumab, Certolizumab Pegol, Golimumab) and a single chimeric protein (Etanercept)." (PMID 37108251, 2023). "In psoriasis, affected keratinocytes produce excessive TNF-α, hence activating dendritic cells to produce IL-12 and IL-23." (PMID 37546687, 2023). "Stoffel sought to characterise anti-TNF-induced inflammatory skin lesions on a histopathologic, cellular, and molecular level compared to psoriasis, eczema (atopic dermatitis), and healthy control skin." (PMID 37175894, 2023). "An ascorbic acid derivative has been shown to ameliorate imiquimod-induced psoriasis-like dermatitis by suppressing inflammatory cytokine (IL-1β and TNF-α)." (PMID 37492568, 2023). "Current evidence suggests that IL-23, IL-6, and TNF-α play pivotal roles in the pathogenesis of psoriasis." (PMID 37275851, 2023). "TNF-α plays an important role in the pathogenesis of psoriasis, and therefore has become the primary target of modern therapy." (PMID 37762693, 2023). "On the other side, besides secreting IL-17, Th17 cells can also release TNF-α, IL-6, IL-21, and IL-22, participating in the development of psoriasis." (PMID 37942312, 2023). "The immune response in psoriasis is characterized by proliferation of Th1, Th17, and Th22 cells resulting in the production of the pro-inflammatory mediators interferon-γ, tumor necrosis factor (TNF)-α, interleukin (IL)-6, and IL-22." (PMID 37895330, 2023). "Many studies have demonstrated that the skin of individuals suffering from psoriasis exhibits notably elevated levels of Tumor necrosis factor TNF-α in comparison to the skin of healthy participants." (PMID 38139369, 2023). "TNF inhibitors, infliximab, adalimumab, and certolizumab pegol are currently offered for treating psoriasis." (PMID 37965393, 2023). "Previous research has demonstrated the inhibitory effect of GA on pro-inflammatory transcription factors, such as STAT3, RORγt, and NF-κB, or cytokines as IL-1β and TNF, which contribute to psoriasis development." (PMID 36754913, 2023). "Nevertheless, GM-CSF has previously been reported as a response biomarker for both anti-TNF and anti-IL-12/23 treatment in psoriasis." (PMID 37631238, 2023). "Psoriasis is centered on the overproduction of Th1‐ and Th2‐related cytokines (e.g., interleukin [IL]‐23, IL‐17, TNF‐α, IL‐22), which is involved in the occurrence and development of its pathogenesis." (PMID 37647442, 2023).